IL1B (interleukin 1 beta)
Diseases named in the same sentence as IL1B in open-access papers (continued):
Sharing a sentence is not in itself a finding about the gene and the disease.
tumor (continued). "The splenocytes of L. braziliensis-treated mice released higher amounts of IL-1β and IL-6 than the PBS control group at day 21 post tumor implantation." (PMID 38457336, 2024). "Together, these data suggest that tumor cell-intrinsic IFN-I signaling is essential for antitumor CD8+ T cell response induction likely via DC activation and IL-1β production in the context of CD47-SIRPα blockade therapy." (PMID 38982116, 2024). "Interleukin-1β (IL-1β): IL-1β is a pro-inflammatory cytokine produced by various cells within the TME, including tumor cells, immune cells, and stromal cells." (PMID 38397971, 2024). "We next examined the expression of the markers identified previously that showed good correlation with tumour volume -ALOX15, IL-1β, CSFR1, CD14 and INHBA - to their expression at the single-cell level in the macrophage subclusters." (PMID 38480935, 2024). "IL-1β not only increased the proliferation, migration, and invasion of two ESCC cell lines but also promoted tumor growth and metastasis in nude mice." (PMID 38762529, 2024). "The selection of cytokines was based on their significant role in regulating the tumor microenvironment, including promoting either the Th1 (IL-2RA, IL-12(p40), IL-15, TNF-α, IL-1β, IL-1RA, and IFN-γ) or the Th2 (IL-4, IL-6, IL-8, and IL-10) profile." (PMID 39768997, 2024). "Similarly, the upregulation of IL-16, a chemotactic cytokine, could attract immune cells to the tumour microenvironment, potentially enhancing anti-tumour responses, and IL-1β can promote immune cell activation, which may contribute to the therapeutic effects of AuNP-P3." (PMID 39682192, 2024). "Half of the trials study the combination of anti-PD-1 and anti-IL-1β, which has shown an increase in CD8+ cytotoxic T cell infiltrate in the tumor." (PMID 38539448, 2024). "ATP from the pyroptosing tumor cells subsequently activates the NLRP3 inflammasome in macrophages, resulting in caspase-1 activation and downstream GSDMD and IL-1β processing and release." (PMID 38391959, 2024). "Abundant CCL22-expression by tumor cells has been reported following combined crosstalk with NK cells and macrophages via the proinflammatory cytokines IFN-γ, TNF-α and IL1β." (PMID 39232378, 2024). "The results showed that TNF-α and IL-1β activated the NF-κB signaling pathway and then promoted OPN expression in tumor cells and tumor cell progression." (PMID 39726047, 2024). "The mRNA relative expression level of NLRP3, Caspase 1, GSDMD, IL-1β and IL-18 in XRZYBXD high dose group were significantly higher than those in the tumor model group by Q-PCR." (PMID 40046008, 2024). "Pro-inflammatory cytokines such as IL-1β, IL-6, IL-8, INF-γ, and TNF-α are known to enhance cell growth, disrupt tumor suppression mechanisms, and impair host immunity, leading to cancer progression." (PMID 39200213, 2024). "Among the mature neutrophils, we identified a distinct subpopulation with high expression of IL-1β, an MDSC marker, and this subpopulation was upregulated in 2208L tumor–bearing mice compared with the non–tumor-bearing mice." (PMID 39287984, 2024). "Early studies have shown that activation of NLRP3 induces adaptive immunity to tumors, and that IL-1β released during this process is required for the priming of IFN-γ-producing, tumor-antigen-specific CD8+ T cells." (PMID 38553639, 2024). "Recent studies have shown that IL-1β is a marker of Inflam-TAMs, and in PDAC, IL-1β+ TAMs promote tumor growth after activation via the PGE2‒IL-1β axis." (PMID 39726047, 2024). "We identified pro-inflammatory cytokines (IL1A, IL1B, IL6), and chemokines (CCL3, CXCL2, CXCL3) that promote inflammation-promoted neoplasia." (PMID 38529274, 2024). "In the current study, we evaluated the regulation of ST6GAL1 by two pro-inflammatory cytokines, IL-1β and IL-6, which are abundant within the PDAC tumor microenvironment." (PMID 39260693, 2024).
tumor (continued). "IL‐17A and TNF synergistically induced the Th17‐promoting cytokines IL‐6 and IL‐1β as well as the Th17‐attracting chemokine CCL20 in mesothelial cells, indicating a reciprocal crosstalk that potentiates the tumor‐promoting role of Th17 cells in OC." (PMID 38566518, 2024). "We show that NLRC4 expression in human tumor cells is sufficient to directly promote DC maturation to secrete IL-12 and IFN-γ in vitro, along with the inflammatory cytokine IL-1β." (PMID 38652550, 2024). "TAMs also release a number of other inflammatory cytokines, such as IL-1β, IL-8, and TGF- β1, which have been shown to drive the EMT of HCC cells, contributing to more aggressive tumour phenotypes and metastasis." (PMID 39684877, 2024). "Overexpression of inflammatory factors promotes tumor development, while targeting inflammatory mediators, such as chemokines, cytokines (TNF-α and IL-1β), and key transcription factors (NF-κB and STAT3), reduces cancer growth and spread." (PMID 38502348, 2024). "High expression of IL-1β in the TME promotes the sustained activation of NFκB, which contributes to tumor initiation." (PMID 39260693, 2024). "NF-κB is overexpressed in the PCa TME and regulates the expression of numerous tumor-promoting genes including cyclin-D1, IL-6, TNFα, VEGF, IL-8 and IL-1β." (PMID 39335188, 2024). "IL-1β is constitutively overexpressed in OSCC and is identified as a key node gene in the tumor microenvironment (TME) of OSCC in vivo." (PMID 38473882, 2024). "Along with the increase of NLRP3, ASC and IL-1β expression levels, an increasing caspase-1 expression profile was obtained for PTX-treated tumor cells compared untreated cells." (PMID 39433537, 2024). "Caspase-1, IL-1β, and IL-18 are down-regulated in NSCLC tumor tissues, and simvastatin activates NLRP3-caspase-1-IL-1β and IL-18 pathways to induce pyroptosis and inhibit NSCLC cell migration." (PMID 38654314, 2024). "The pro‐tumorigenic activity of 2‐ME was accompanied by lower CD3+ T‐cell numbers in the tumor microenvironment (TME) and high levels of the pro‐inflammatory cytokine interleukin (IL)‐1β." (PMID 38600057, 2024). "Increased IL-1β drives the further upregulation of HIF-1α in HCC cells, mediating an epithelial-to-mesenchymal transition (EMT), leading to more aggressive tumours and metastasis." (PMID 39684877, 2024). "It has previously been shown that chronic hypoxic conditions, such as those found within a large majority of HCC tumours, are able to induce the TAM “M2-like” phenotype, resulting in an upregulation and secretion of IL-1β." (PMID 39684877, 2024). "Key genes, including IL6, IL1B, and COL1A1, emerged from GSEA and tumor prediction analysis, highlighting the broad relevance of these genomic alterations across diseases." (PMID 39635438, 2024). "Proinflammatory cytokines such as IL-6, IL-1α, IL-1β and IL1RA are primarily secreted by activated myeloid cells and play critical roles in an anti-tumor immune response." (PMID 38400933, 2024). "This pattern is completely logical as inhibition of IL-10 allows for less immunosuppression, more angiogenesis, and more VEGF, IL-1β, TNF-α, IL-6, MMP-9, and NF-κB activation, which encourages tumor volume." (PMID 39451257, 2024). "Lastly, TAM5, enriched in the primary tumor (PT), exhibited high expression of various immunosuppressive factors, including IL1A, IL1B, IL1RN, and IL6." (PMID 39236316, 2024). "Taken together, these results establish a paracrine circuit in which optic nerve neuronal injury results in glutamate release, oligodendrocyte IL-1β and TAM Ccl5 production, and tumor formation." (PMID 38308315, 2024). "Classically activated macrophages (M1) exert anti-tumoral activities by secreting IL-1β, IL-12 and TNF-α, while alternatively activated macrophages (M2) fuel tumor growth through immune suppression and promotion of angiogenesis and metastasis." (PMID 39335188, 2024).
tumor (continued). "The proinflammatory cytokines of IL‐1β, IL‐17, MIF, and TNF‐α were significantly increased in tumor represented complex immunity dysregulation and possible molecular mechanisms due to dysbiosis of the microbiome." (PMID 38041547, 2024). "An analysis of OS tumor infiltrates by scRNA-seq revealed that the majority of TAMs in OS exhibited M2 polarization, and they may support immune escape and metastatic progression by secreting various immunosuppressive and angiogenic factors, such as IL-1β, IL-4, IL-10, and TGF-β." (PMID 38334625, 2024). "Tumor-induced cytokines such as TNF-α, interleukin 1 beta, and IL-6 contribute to the inhibition of albumin gene expression in cachexia." (PMID 38339365, 2024). "In a separate validation experiment, we confirmed that Il-1β, Spon1, and Cfb showed significantly increased expression in TIMs in the LN2E1 model when compared with IMs from the BM of non–tumor-bearing mice." (PMID 38716730, 2024). "To determine the roles of IL1α, IL1β and IL8 in promoting tumor growth, we knocked down the expression of these three genes using shRNAs and measured the tumor size after 42 days." (PMID 37551997, 2023). "The effects of other intercellular substances in the tumour microenvironment, such as ATP, HMGB1, IL1β, and LDH, are still uncertain." (PMID 37211606, 2023). "Our results showed that pro-inflammatory and tumor-promoting factors MMP9, IL-8, OSM, IL-1β, TNF-α, CXCL3, and ROS all increased to varying degrees after OCOs stimulation." (PMID 37644468, 2023). "The level of IL-1β, IL-6 and TNF-α were increased in tumor mice after DSF treatment, while the level of IL-4, IL-10 and TGF-β were increased after DSF treatment." (PMID 37305383, 2023). "In our previous study, we revealed that deactivation of STING signaling in tumor cells increases p-STAT3 signaling, resulting in interleukin-6 (IL-6) and IL-1β production in the tumor microenvironment." (PMID 36622166, 2023). "The IL-1β-dependent activation of NF-κB stimulated the c-Jun N-terminal kinase (JNK) signaling pathway, leading to tumor proliferation, invasion and progression." (PMID 37081882, 2023). "Although the level of IL-1β that is subsequently produced cannot activate CD8+ T cells, they can induce CD4+ T cells to produce IL-17, thus promoting tumor growth and angiogenesis." (PMID 37497237, 2023). "In patient-derived primary tumor tissues, the expression of STAT3 and IL-1β displayed a positive correlation." (PMID 36922898, 2023). "IL-1β and tumor necrosis factor (TNF)-β reportedly contribute to forming the cold tumor immune microenvironment by suppressing TILs." (PMID 37686634, 2023). "Subsequently, to assess how IL‐1β blockade reshaped the TIME, we determined the levels of PD‐L1, F4/80, and granzyme B in ID8 tumor tissues with IHC staining." (PMID 37009412, 2023). "For example, in GBM tumor cells, IL-1β induces an HIF1A/IL-1β autocrine loop via activating Wnt-1 and RAS, which both contribute to the increase of HIF-1A." (PMID 37538397, 2023). "This orchestrated process involves the release of inflammatory factors, such as IL-18 and IL-1β, which attract dendritic cells and CD8+ T cells into the tumor tissue, activating antitumor immunity and hindering tumor progression." (PMID 38066523, 2023). "Inhibiting IL-1B, however, may or may not be helpful for patients based on its polymorphism, depending on the cancer kind or stage, the primary type of immune cells present in the tumor microenvironment, and the anti-cancer treatment utilized." (PMID 37894904, 2023). "It has been seen that CMF treatment enhances the IL-1β, IL-6, and TNF-α in the tumor-bearing animal." (PMID 37631080, 2023). "We found that the SAA signaling significantly influenced the releasing of many TH1 / TH2 polarization and anti-tumor immunity related cytokines including IFN-α, IL-1β, IFN-γ, IL-4 and etc.." (PMID 37925492, 2023).
tumor (continued). "During tumor progression, CAAs support CRC onco-inflammatory milieu through release of proinflammatory cytokines, including IL1-β, IL-6, IL-8, and TNF-α that modulate the innate and adaptive immune response." (PMID 37760840, 2023). "IL-17-induced inflammatory mediators, such as IL-1β, IL-6, and TGF-β, promote a proangiogenic and immune suppressive tumor environment that enhances tumor growth." (PMID 37631976, 2023). "A modest correlation was also determined between IL-1β and FN-EDA gene expression in patient tumor specimens." (PMID 36922898, 2023). "These pathways further increase the expression of IL1α, IL1β and IL8 to increase the survival of TNBC when they interact with macrophages, and enhance the tumor growth, metastasis of TNBC, and macrophage infiltration into tumor sites." (PMID 37551997, 2023). "The cytotoxic ability of IL-36γ–treated neutrophils was enhanced by cytokines, such as IL-1β, IL-2, or TLR ligands, such as LPS or irradiated tumor cells." (PMID 37317970, 2023). "Pro-inflammatory cytokines, such as IL-1α, IL-1β, IL-6, and TNF, showed higher amounts in the saliva of patients with OSCC, indicating the involvement of the inflammatory environment in tumor progression." (PMID 37686462, 2023). "We used IHC to detect the expression of IL-1β and MMP9 in 10 sensitive and 13 resistant tumor tissues from MSI-H/dMMR patients." (PMID 37106440, 2023). "Most of PRGs displayed higher expression levels in tumor samples compared with normal controls except for AIM2, IL1B, and NLRC4, of which the mRNA expression was decreased in tumor samples." (PMID 37051536, 2023). "CD103+ DCs from tumor-draining lymph nodes express increased levels of PD-L1, and blockade of PD-L1 and PD-1 mitigates DC dysfunction in terms of TNF-α, IL-12, and IL-1β production and enhances T-cell-stimulatory capacity." (PMID 36949244, 2023). "The effect of TAM with active STAT3 leads to the secretion of interleukin (IL)-1β, which promote GBM growth by also allowing the activation of STAT3 and nuclear factor-kappa B (NF-kB) signaling in tumor cells." (PMID 37190507, 2023). "Consistent with the literature, we observed that UA downregulated elevated IL-6, IL-1β, and TNF-α levels in the serum of LLC tumor-bearing mice and inhibited elevated phosphorylation of NF-κB and STAT3." (PMID 37190306, 2023). "IL-1β has been demonstrated in chronic inflammation and is predominantly expressed in the TME by tumor-infiltrating macrophages, promoting tumor development and metastasis." (PMID 37068081, 2023). "According to this study, BC patients had significantly lower serum concentrations of IL-4 and significantly higher quantities of the tumor markers, CA15-3, IL-1β, and VEGF." (PMID 36619680, 2023). "We observed a significant increase in the frequency of PD1+CD8+ T cells in tumors of mice bearing the Arf1‐ablated tumor cells, whereas the increase was completely abolished after treatment with both anti‐IFNAR1 and anti‐IL‐1β antibodies." (PMID 37786300, 2023). "Pharmacological antagonizing Il1 signaling locally in tumor-bearing mice extended survival time and decreased TAM infiltration, which was opposite of what was observed with Il1a–/–;Il1b–/–;Ntv-a mice." (PMID 37733448, 2023). "Upregulate ZO-1, occludin, CD8 CTLs, ATP, and glucose of tumor-infiltrating lymphocytes; downregulate TNF-α, IL-1β, and PD-1." (PMID 38068759, 2023). "IL-21 released by IL-1β-stimulated TH9 cells induced IFNγ secretion from CD8 and NK cells in tumor-bearing mice, resulting in tumor growth inhibition." (PMID 37189417, 2023). "Bioinformatic analysis of human tumor samples showed that UM has significantly lower expression of NLRP3 and IL‐1β compared with CM." (PMID 36707938, 2023). "Relative vessels number, necrosis areas and Ki-67 index were assessed microscopically; tumor volumes were determined by 3D reconstruction from histological images; serum levels of HIF-1α, IL-1β, and TNFα were determined by ELISA." (PMID 37542119, 2023).
tumor (continued). "A clinic analysis of TCGA revealed that PRKCDBP, Caspase‐1, IL‐1β, NLRP3 and Caspase‐4 were expressed at low level in tumour tissues than in the normal tissues in LUAD and LUSC." (PMID 36696967, 2023). "PPP2CA downregulation enhances NF-κB signaling and promotes macrophage expression of IL-1β, IL-6, and TNF-α, which contributed to tumor progression." (PMID 36624542, 2023). "Anakinra or canakinumab (anti-IL-1β monoclonal antibody) reduces EMT of BC cells and the number of tumor cells moving into the circulation, which ultimately reduces the bone metastasis of BC." (PMID 36765683, 2023). "In this regard, a significant increase in lymphocyte-activating IL2 was observed along with inflammasome-related IL1β and IL18, which play dual roles in cancer progression and anti-tumor immune responses." (PMID 36831596, 2023). "Correspondingly, the inflammatory factors of IL-1β, TNF-α, and IL-6 were increased in the MD@SA hydrogel group, offering a robust immune environment to restrict tumor regrowth." (PMID 37981704, 2023). "Tumor-derived GM-CSF, IL-6, IL-1β, TGF-β, IL-13, IFN-γ, CXCL5 have also been found to regulate MDSC accumulation and the polarization of tumor-infiltrating granulocytic MDSC (G-MDSC) toward an immunosuppressive phenotype." (PMID 38304256, 2023). "Considering the strong effect of combined Il1a and Il1b loss on MCP levels in tumors together with the strong effect on monocyte recruitment shown in scRNA-Seq data, we sought to determine whether genetic deletion of both Il1a and Il1b would further extend survival of tumor-bearing mice." (PMID 37733448, 2023). "Expansion and activation of MDSCs in the TME are also dependent on cytokines secreted by tumor cells, such as interferon (IFN)-γ, IL-1β, IL-4, and IL-6 or activated immune cells like GM-CS, G-CSF, and VEGF." (PMID 37410164, 2023). "In consistency with these studies, ETP-treated and F30-HSCs exhibited higher levels of pro-inflammatory gene expression, such as IL-1β, IL-6, CXCL1 and CXCL9, as well as MMPs (for tumor metastasis) than controls." (PMID 37649614, 2023). "IL-4, TGFβ and IL-8 were assessed in low amounts (471 to 820 pg/mg of tumor); CCL2, IL-12, IL-6 and IL-10 in moderate amounts (2825 to 3440 pg/mg of tumor); and IFNγ, TNFα, IL-1β and IL-2 in high amounts (6293 to 13,492 pg/mg of tumor)." (PMID 37526660, 2023). "Inflammatory mediators such as TNF-α, IL-1β, IL-6, and IFN-γ promote an increase in blood supply to the tumor." (PMID 37894468, 2023). "The first tested condition was the activation of cytokines involved in polarizing macrophages to a cytotoxic tumor-eliminating phenotype: IFNG, IFNB, TNFA, and IL1B." (PMID 37283734, 2023). "Hereof, increased levels of IL1β, IL8, MCP1 and TNFα have been related to tumour progression and metastasis in HNSCC." (PMID 37460712, 2023). "This was confirmed by the observation of a significant positive correlation between IL‐1β and CCL2 levels in ID8 tumor tissues and LLC tumor tissues." (PMID 37009412, 2023). "Recently, it was reported that inhibiting the SREBP pathway prevents HCC by downregulating tumor-promoting cytokines, including IL-6, TNF-α, and IL-1β." (PMID 37434430, 2023). "These inflammatory factors include pro-inflammatory cytokines IL-1β, IL-18, and DAMPs such as ATP, DNA, or HMGB1, and in doing so they regulate the proportions of tumor-infiltrating immune cells such as T cells, NK cells, DCs, monocytes, and MDSCs." (PMID 36831197, 2023). "A significant decrease in levels of interferon γ (IFNγ), IL1β, interleukin 8 (IL8) and monocyte chemoattractant protein-1 (MCP1) was identified in both gas plasma-treated WT and RE tumours." (PMID 37460712, 2023). "High expression of TNF-α, IL-1β, NOS2 and CD86 implied the polarisation of HF-CAR-PMs inside HER2+ tumours toward M1 phenotype." (PMID 37386139, 2023).